PICALM (phosphatidylinositol binding clathrin assembly protein)
Diseases named in the same sentence as PICALM in open-access papers (continued):
Sharing a sentence is not in itself a finding about the gene and the disease.
gastric cancer (10 papers, 2021 to 2025). A primary or metastatic malignant neoplasm involving the stomach. "Alternative splicing of PICALM regulated by long non-coding RNA can weaken the chemoresistance of gastric cancer." (PMID 39726754, 2024). "CRNDE restrains chemoresistance in gastric cancer through SRSF6-mediated alternative splicing of PICALM." (PMID 37194105, 2023). "CRNDE could regulate the progression and chemoresistance of CRC via modulating the expression levels of miR-181a-5p and the activity of Wnt/β-catenin signaling, and CRNDE attenuates chemoresistance in gastric cancer via SRSF6-regulated alternative splicing of PICALM." (PMID 36911393, 2023). "In gastric cancer, autophagy induced by lncRNA CRNDE through the SRSF6/PICALM pathway during 5‐FU treatment promoted chemoresistance, similar to L‐OHP." (PMID 37837401, 2023). "In principle, SRSF6 promotes phosphatidylinositol-binding clathrin assembly protein (PICALM) exon 14 inclusion to produce a full-length PICALM protein, which is required for the autophagy-induced resistance of gastric cancer cells to oxaliplatin and 5-FU." (PMID 34917618, 2021). "Moreover, in vivo experimental studies recently showed that by modulating PICALM splicing through SRSF6, lncRNA CRNDE enhances the response of gastric cancer cells to chemotherapy." (PMID 37482612, 2023). "In addition, PICALM knockdown did not affect the therapeutic effects in breast and stomach cancers in vitro." (PMID 38935046, 2024). "In gastric cancer (GC), lncRNA CRNDE directly binds to splicing protein SRSF6 to reduce its protein stability, which in turn reduces PICALM alternative splicing, triggering a significant switch from the short to long isoform to induce attenuated chemoresistance." (PMID 39937018, 2025).
leukemia (8 papers, 2012 to 2026). A malignant (clonal) hematologic disorder, involving hematopoietic stem cells and characterized by the presence of primitive or atypical myeloid or lymphoid cells in the bone marrow and the blood. "In addition, structural chromosomal abnormality involving genetic locus where PICALM is localized has been implicated in human hematopoietic malignancies such as leukemia and lymphomas." (PMID 24690091, 2014). "Leukemias with PICALM translocations also have PICALM haploinsufficiency, which could manifest as a relative deficiency of PICALM protein expression." (PMID 22952941, 2012). "The resulting defective endocytosis could render PICALM-deficient leukemia cells relatively iron deficient, and therefore more sensitive to reduced levels of extracellular iron." (PMID 22952941, 2012). "In leukemias and lymphomas, PICALM has been identified as a translocation partner for the AF10 transcription factor gene (10p12), and also for the Mixed Lineage Leukemia (MLL) histone methyltransferase gene (11q23)." (PMID 22952941, 2012). "PICALM::MLLT10 translocated leukemia is primarily an epigenetically driven disease." (PMID 41532548, 2026). "Acute myeloid leukemia is prioritized as the most significant m6A associated disease, where m6A-regulated genes NSD1, PICALM, and ABL2 are OMIM-annotated disease genes, suggesting that they may be potential m6A-associated biomarkers in leukemia." (PMID 30601803, 2019). "This raises the possibility that iron chelation could be of benefit in the treatment of patients with PICALM haploinsufficient leukemias." (PMID 22952941, 2012). "Mature TCRγδ + PICALM::MLLT10 positive T‐ALL responds well to standard treatment, whereas TCR‐PICALM::MLLT10 positive T‐ALL has a strikingly inferior outcome, suggesting that an earlier stage of leukemia stem cells (LSCs) is insensitive and resistant to conventional therapy." (PMID 38895061, 2024).
tauopathies (8 papers, 2017 to 2023). "In postmortem human tissues, PICALM immunoreactivity is associated with pathological tau in the AD brain and in other tauopathies such as PSP and Pick disease." (PMID 36552756, 2022). "PICALM was found to associate with both 3R and 4R tau inclusions in AD and primary tauopathies, and soluble PICALM levels were inversely correlated with phosphotau, suggesting a biological link between this protein involved in clathrin‐mediated endocytosis and tau." (PMID 32400971, 2020). "Such reduction of PICALM seems related to the fact that PICALM is a substrate of both calpain and caspase-3 that are activated in the brains of AD and other tauopathies." (PMID 36552756, 2022). "PICALM levels are decreased and PICALM co-localizes with tau inclusions in AD and in other tauopathies." (PMID 29258615, 2017). "Moreover, the expression of PICALM was reduced and co-localized with hyperphosphorylated tau in AD patients, possibly indicating a role of PICALM in tauopathy." (PMID 28116548, 2018).
cognitive decline (7 papers, 2020 to 2023). "In elderly subjects, PICALM GG genotype is associated with lower hippocampal volume, decreased entorhinal cortex thickness and earlier cognitive decline." (PMID 32372909, 2020). "Phosphatidylinositol Binding Clathrin Assembly Protein (PICALM) was another candidate gene whose methylation associated with cognitive decline in blood cells of AD patients." (PMID 32211026, 2020). "Our finding coincides with the previously reported studies where reduced expression of PICALM was observed in AD and murine brain endothelium associated Aβ pathology and cognitive decline." (PMID 33062432, 2020). "For PICALM, lower protein levels explained 14.3% of faster cognitive decline, in line with the previous reports showing the decreased PICALM protein in AD13." (PMID 35115553, 2022). "For example, ischaemia will raise [Ca2+]i which can result in calpain cleaving PICALM, and indeed PICALM levels are lower in human AD, correlating both with an increased Aβ level and with cognitive decline as assessed with the Mini Mental State Exam." (PMID 32865691, 2020).
amyloid (6 papers, 2015 to 2025). "This seminal finding marks the first of its kind, mechanistically answering the integral question on the relation between the AD risk factor PICALM, amyloid load and LRP1 function." (PMID 26236233, 2015). "AD-associated risk genes, including APP, PICALM, and RBFOX1, were positively correlated with plasma cells, activated CD4+ T cells, and Tregs, linking amyloid-related pathways to adaptive immune activation." (PMID 41567547, 2025). "As there are multiple implications of PICALM in the regulation of Aβ pathology (autophagy, APP processing, transcytosis), it is not surprising that there are some contradictory observations in transgenic models of amyloid pathology with reduced expression of PICALM." (PMID 36552756, 2022).
Parkinson disease (5 papers, 2014 to 2025). A progressive degenerative disorder of the central nervous system characterized by loss of dopamine producing neurons in the substantia nigra and the presence of Lewy bodies in the substantia nigra and locus coeruleus. "Patients with Parkinson’s disease have reduced PICALM mRNA expression in their blood, whereas patients with AD have higher levels." (PMID 39975850, 2025). "Interestingly, the risk G allele of another PICALM polymorphism, rs3851179, was associated with general cognition impairments in >70-year-old Parkinson’s disease patients but not in ≤70-year-old patients." (PMID 28116548, 2018).
acute myeloid leukemia (4 papers, 2019 to 2024). Acute myeloid leukemia (AML) is a group of neoplasms arising from precursor cells committed to the myeloid cell-line differentiation. "Patient 6 (P6) M/40Y was an acute myeloid leukaemia (AML) patient with PICALM::MLLT10 fusion transcript habouring a breakpoint in PICALM exon 19 and MLLT10 exon 9 (NM_007166.4: r.-304_1944::NM_001195626.3:r.700_*1647)." (PMID 38493200, 2024). "It is still confused whether PICALM::MLLT10 can solely correspond to acute myeloid leukemia (AML) or acute lymphoblastic leukemia (ALL) or acute leukemias of ambiguous lineage (ALAL)." (PMID 38895061, 2024).
Brain atrophy (4 papers, 2010 to 2022). Partial or complete wasting (loss) of brain tissue that was once present. "For the primary analysis, we used an additive model to assess whether the following late onset AD-associated variants influence brain atrophy and cognitive dysfunction in MS patients: PICALM (rs3851179), CR1 (rs6656401), CLU (rs11136000), PCK1 (rs8192708), and ZNF224 (rs3746319)." (PMID 21152065, 2010). "The purpose of the present study was to analyze whether the genotypes of PICALM rs3851179 were related to AD brain atrophy, Aβ level, and tau level of CSF." (PMID 36552141, 2022). "Given that normal aging might play a more important role in causing brain atrophy in the stage of NC than MCI/AD, it can be thus inferred that the potential pathways by which PICALM variations act may be possibly associated with fighting against normal aging of posterior cingulate." (PMID 27117083, 2016).
late-onset Alzheimers disease (4 papers, 2011 to 2022). This is the most common form of the disease, which happens to people age 65 and older. "Recent GWAS and subsequent confirmation studies reported several single-nucleotide polymorphisms (SNPs) at the CLU, CR1 and PICALM loci in association with late-onset Alzheimer's disease (AD)." (PMID 21912625, 2011).
lymphoma (4 papers, 2014 to 2021). A malignant (clonal) proliferation of B- lymphocytes or T- lymphocytes which involves the lymph nodes, bone marrow and/or extranodal sites. "In contrast, critical components of CME, EPN1 and PICALM, were not essential in Ramos cells or most other lymphoma cell lines (Fig EV4D)." (PMID 34323351, 2021).
anemia (2 papers, 2014 to 2017). A reduction in the number of red blood cells, the amount of hemoglobin, and/or the volume of packed red blood cells. "And PICALM knockout mice are found to develop iron deficiency anemia." (PMID 28915649, 2017). "Consistent with a critical role for PICALM in iron homeostasis, PICALM-deficient mice suffer from severe anemia and poor erythroid development and, at the cellular level, show reduced transferrin uptake; iron supplementation ameliorates some aspects of PICALM deletion." (PMID 24618820, 2014).
depression (2 papers, 2017 to 2025). "This study suggests that PICALM mRNA level in human blood could be a helpful diagnostic tool for distinguishing neurodegenerative illnesses from major depression." (PMID 39975850, 2025). "Accordingly, we speculate that PICALM may affect the occurrence of depression in patients with T2DM via a number of molecular mechanisms, particularly the cellular autophagy pathway." (PMID 28779132, 2017).
hippocampal atrophy (2 papers, 2020 to 2023). "There are significant associations between several SNPs in the PICALM locus with AD-related phenotypes such as the age of onset, hippocampal atrophy, cognitive functions, and tau or Aβ levels in CSF." (PMID 36982820, 2023).
iron deficiency (2 papers, 2012 to 2017). "Taken together, we conclude that the iron deficiency phenotype of fit1 mice is attributable to PICALM deficiency, and we have identified the carboxy-terminus of PICALM as the essential region." (PMID 22952941, 2012). "The increased expression of TfR in PICALM-deficient cells likely reflects a state of relative iron deficiency, characterized by increased TfR mRNA stability and protein translation, and is consistent with the iron deficiency phenotype originally described in the fit1 mutant mice." (PMID 22952941, 2012). "Murine embryonic fibroblasts (MEFs) that are deficient in PICALM display several characteristics of iron deficiency (increased surface TfR expression, decreased intracellular iron levels, and reduced cellular proliferation), all of which are rescued by retroviral PICALM expression." (PMID 22952941, 2012). "This is of importance because the relative reduction in TfR internalization seen in PICALM-deficient cells could be due to a saturation of the cellular endocytic machinery resulting from the overexpression of TfR secondary to iron deficiency." (PMID 22952941, 2012). "Consistent with a defect in TfR endocytosis, PICALM-deficient MEFs display features of iron deficiency, including increased TfR expression at the protein and transcript levels, reduced concentrations of intracellular iron, and a defect in proliferation that can be restored by iron supplementation." (PMID 22952941, 2012). "Furthermore, the proliferation defect of PICALM-deficient cells appears to be due to iron deficiency, as iron supplementation restores their proliferation to normal levels." (PMID 22952941, 2012).
malaria (2 papers, 2021 to 2023). Malaria is a serious and sometimes fatal disease caused by a parasite that commonly infects a certain type of mosquito which feeds on humans. "The hits that showed significant PICALM mRNA upregulation in Eahy926 cells were the anti-malaria drug artesunate and antimetabolite anti-psoriatic drug 6-azauridine." (PMID 36707892, 2023).
neuroblastoma (2 papers, 2019 to 2024). Neuroblastoma (NB) is the most common solid, extracranial childhood tumor. "Eventual loss of PICALM caused by risk SNPs could be exacerbated by an abnormal cleavage of PICALM by calpain and caspase-3, creating 25 and 50 kDa fragments as assessed in human brain extracts and neuroblastoma cells." (PMID 31159836, 2019). "Despite these effects, PICALM generally does not appear to affect the general clathrin-mediated endocytosis uptake of cargo, but only that of specific proteins, such as vesicle-associated membrane proteins (VAMPs; i.e. VAMP-2, VAMP-3 and VAMP-8), as detected in HeLa and neuroblastoma cell lysates." (PMID 31159836, 2019).
Onset (2 papers, 2016 to 2021). The age group in which disease manifestations appear. "Through genome-wide association studies and other methods, it has been found that many genes related to lipid metabolism, immune response, and endocytosis are correlated with the occurrence of late-onset AD, including APOE, TREM2, PICALM, and CLU." (PMID 33806413, 2021).
viral infection (2 papers, 2019 to 2024). "It affects the susceptibility to viral infection in the brain 35 and is expressed in endothelial cells in human brain tissue 36, suggesting that PICALM may be involved in severe HFMD caused by EV-A71 infection." (PMID 31853228, 2019). "Collectively, our findings provide evidence that exosomal miR-155 plays a role in host-pathogen interactions by mediating EV-A71 infection via the repression of PICALM; these results provide insights into the regulatory mechanisms of viral infection." (PMID 31853228, 2019). "In contrast, the downregulation of TREM2 and PICALM gene products increases AD risks but may promote viral infections." (PMID 37962454, 2024). "Moreover, we presented evidence that exosomal miR-155 can be transferred to recipient cells and suppress viral infection by targeting PICALM." (PMID 31853228, 2019). "Biological information analysis and subsequent studies demonstrated that exosomal miR-155 suppressed PICALM expression by binding to the PICALM 3'UTR, thus inhibiting viral infection." (PMID 31853228, 2019). "PICALM is a key component of clathrin-mediated endocytosis (CME) and participates in virus infection." (PMID 31853228, 2019).
acute leukemia (1 paper, 2024). A clonal (malignant) hematopoietic disorder with an acute onset, affecting the bone marrow and the peripheral blood. "The 2022 WHO classification further mentioned that genomic findings such as PICALM::MLLT10 fusions are enriched in mixed‐phenotype acute leukemias (MPALs), which belong to acute leukemias of ambiguous lineage (ALAL) but need more data." (PMID 38895061, 2024).
allergic rhinitis (1 paper, 2020). Inflammation of the nasal mucous membranes caused by an IgE-mediated response to external allergens. "In the UKB cohort, CD33 variant rs3865444 had nominal association with asthma (p = 2.84 x 10−4), while CD2AP variant rs9349407 had nominal association with UC (p = 0.0004) and PICALM variant rs3851179 had nominal association with hay fever or allergic rhinitis (p = 4.42 x 10−4)." (PMID 33152005, 2020).
Atrophy (1 paper, 2016). Any weakening or degeneration, especially through lack of use. "In the present analysis, we found that PICALM genetic variations were more inclined to be associated with atrophy rate in NC individuals." (PMID 27117083, 2016). "Compared to NC population, the trend of associations of PICALM variations with atrophy rate of posterior cingulate in MCI population were consistent." (PMID 27117083, 2016).
autoimmune disease (1 paper, 2018). A disorder resulting from loss of function or tissue destruction of an organ or multiple organs, arising from humoral or cellular immune responses of the individual to their own tissue constituents. "PICALM, PVRL2, PVR, and CLU have shown to be related to systemic, an autoimmune disease characterized by vascular injury and debilitating tissue fibrosis." (PMID 30666269, 2018).
congenital heart defects (1 paper, 2014). "Understanding the role of PICALM in OFT development may aid in future molecular and genetic investigations into other congenital heart defects of various species." (PMID 24898977, 2014).
diabetes (1 paper, 2024). "We found select associations between higher MDMX, PICALM, OT-R protein levels and either gravidity, diabetes, BMI, maternal age, or neonatal weight, and correlations only between PICALM-OT-R (p < 2.7 × 10–8), PICALM-V1aR (p < 0.006), and OT-R-V1aR (p < 0.001)." (PMID 38594674, 2024).
Hypertension (1 paper, 2024). The presence of chronic increased pressure in the systemic arterial system. "Protein-glutamine gamma-glutamyltransferase 2 (TGM2), which co-immunoprecipitated with MDMX and PICALM, catalyzes protein cross-linking, is considered a bridge between inflammation and hypertension, and is upregulated in preeclampsia." (PMID 38594674, 2024).
Lymphatic Metastasis (1 paper, 2022). Transfer of a neoplasm from its primary site to lymph nodes or to distant parts of the body by way of the lymphatic system. "Spearman correlation analysis confirmed that expression of PICALM was positively correlated with stage and lymphatic metastasis." (PMID 35501863, 2022).
myeloma (1 paper, 2014). "It is important to determine whether iron chelation is a potential novel therapy for myeloma patients with high expression of PICALM and iron levels." (PMID 24690091, 2014). "Therefore, it is worthy to investigate whether PICALM over-expression would enhance cell proliferation by boosting iron uptake in myeloma patients." (PMID 24690091, 2014).
neuropathy (1 paper, 2024). A disorder affecting the nervous system that manifests with pain, tingling, numbness, and/or muscle weakness. "Chronic CHIKV patients also show upregulation of genes associated with neuronal death (FOXO3, MCL1, ZNF746, and PICALM) and T-cell differentiation, which may contribute to secondary neuropathy symptoms." (PMID 39596565, 2024).